CD34 (CD34 molecule)
Diseases named in the same sentence as CD34 in open-access papers (continued):
Sharing a sentence is not in itself a finding about the gene and the disease.
cancer (continued). "Myeloid-derived suppressor cells (MDSCs; CD34+CD33+CD13+CD15(−)) are a population of myeloid progenitor cells that have been observed to be key players in chronic inflammation and cancer development." (PMID 36358879, 2022). "Among the results, the expression levels of CD34, IL6, SPI1, and SELL showed significant expression differences in 16, 12, 12, and 11 cancer types, respectively, especially in BRCA." (PMID 33869191, 2021). "The tumorsphere assays revealed that the CD34+CD90+OV-6+csVimentin+cells had the ability of self-renewal, which is one of the major features of cancer stem cells." (PMID 34685577, 2021). "Some cancer cells begin to express stem cell markers, such as CD44 and CD34, and their self-renewal, proliferation, and drug resistance are significantly increased." (PMID 34553071, 2021). "In the present study, we show that high expression of CD34 and α6-integrin within UV-induced mouse SCC recapitulated cancer-initiating cells." (PMID 33123267, 2020). "OKN-007 treated mice also had significantly decreased CD34 expression compared to both the untreated and LDN-193189 treated mice, making this a promising therapeutic anti-cancer agent." (PMID 33168005, 2020). "Previous studies have opined that there were many vascular markers such as factor VIII, CD31, CD34, and CD105 for marking microvessels endothelium in malignant tumors." (PMID 33267784, 2020). "Therefore, the aim of this study was to generate NK cells by invitro differentiation of human derived UCB CD34 cells and to expand these NK cells in vitro using the best available methodology and finally test the cytotoxic potential of these NK cells against different cancer cell lines." (PMID 32592353, 2020). "When Bonnet & Dick showed that in Acute Myeloid Leukaemia (AML), this subset of cells had an exclusive phenotype (CD34+/CD38–), a new model to explain cancer cell heterogeneity was proposed: cancer stem cells (CSC)." (PMID 31834886, 2019). "This was further corroborated by a decrease in the mRNA expression of various AML stem cell makers like (CD47, CD34 and CD126) upon treatment of these cancer cells with triptolide for 24 h." (PMID 31109340, 2019). "Here, we studied the ability of transplanted human cancer cells to form primary tumors and metastasize in humanized immune system (HIS) mice created by transfer of CD34+ human hematopoietic stem cells." (PMID 30120895, 2018). "In a phase I clinical trial in patients with advanced cancer, LY2510924 peptide mobilized CD34+ HSCs and neutrophils with favorable pharmacokinetic and safety profiles." (PMID 29212254, 2017). "Telomeric circular DNA was detected in all three sorted cell populations in K14Cre;TRF2f/f;Terc-/- SCC cells, and in CD34-Lgr6- basal cells from K14Cre;TRF2+/+;Terc+/+ cancers." (PMID 29113290, 2017). "Although cancer genes also emerged from GRIP targets and upstream regulators in normal CD34+ cells, predicted upstream regulators included cytokines that were not targeted by proviral insertion." (PMID 27097319, 2016). "CD133 was first discovered as a surface antigen on CD34+ hematopoietic stem cells and has been used in combination with other cell-surface markers, including CD24, CD34, and CD44, to isolate cancer stem cells (CSCs) from a variety of tumors." (PMID 26515729, 2015). "Cell morphology of cancer cells and positive staining for CD34 indicated that cells expressing TLR7 and TLR8 were indeed cancer cells." (PMID 26134824, 2015). "The correlations between cancer stroma VASH1 expression level and expressions of CD34, D2-40, VEGF-A, VEGF-C in cancer tissues were analyzed." (PMID 25797264, 2015). "In this work, we report conditions for basal and high yield in vitro expansion of a CD133+/CD34+ subset of progenitor cells from human UCB stimulated by estradiol, a hormone involved in both normal cell proliferation and development of cancer." (PMID 17559657, 2007).
cancer (continued). "CD34 is well known to highly express on a variety of cancer stem cells, but not in mature blood and lymphoid cells and plays an important role in blocking cell differentiation." (PMID 41296384, 2025). "Additionally, Luminal cancers had higher numbers of CD10(+) and CD34(+) telocytes than the HER2(+) subgroup." (PMID 40724542, 2025). "CD34-positive lymphatic vessels were not identified in normal tissues but were found in cancer tissues, suggesting that CD34-positive lymphatic vessels are neoplastic lymph vessels." (PMID 40243510, 2025). "Additionally, we compared the differences in FYB1 expression between normal and cancer cell lines and found that both mRNA and protein levels of FYB1 in cancer cell lines were higher than in CD34+ HSPC." (PMID 38700746, 2025). "We first verified whether CD34+DNAM-1brightCXCR4+ “inflammatory” CLP that are detected in PBMC of patients with acute or chronic infections could also be detected in cancer patients." (PMID 38390333, 2024). "Indeed, DEN exposure reduced UCB-derived CD34+ cell proliferation capacity, in line with the observation of the antiproliferative effect of DEN in both healthy and cancer settings, and self-renewing potential." (PMID 37798139, 2024). "Importantly, progenies from both CD34+DNAM-1brightCXCR4+ and Lin-CD56-CD16+CD7- purified cells derived from cancer tissue, uninvolved tissue, and PBMC consistently expressed inhibiting NK cell receptors (KIRs and NKG2A)." (PMID 38390333, 2024). "A significant positive correlation was found between the expression of POSTN (in cancer cells/CAFs) and the expression of the analyzed pro-angiogenic factors (CD31, CD34, CD105, and VEGF-A) and MVD in the entire population of patients with NSCLC and individual histological subtypes (AC, SCC)." (PMID 39272978, 2024). "Notably, CD34, IL7R, NRP1, GZMB, FGF7, and ENO2 exhibited significant expression in cancer stem cells, CD4+ memory cells, regulatory T cells, NK cells, fibroblasts, and neurons, respectively." (PMID 38846945, 2024). "The distinctive features include absence of carcinoma (in situ or invasive) and presence of tortuous and anastomosing vascular channels lined by atypical endothelial cells, which are positive for CD34, CD31, and ERG." (PMID 38403668, 2024). "CD44 is highly expressed within normal, CML and AML CD34+CD38+ and CD34+CD38− BM cells [53•], likely making it unsuitable as a CML LSC biomarker and a cancer-specific therapeutic target, but downstream signalling may be targetable." (PMID 36780103, 2023). "Despite all the information obtained from past studies, the precise mechanisms by which CD34 contributes to cancer development and progression are complex and not yet fully understood." (PMID 37241170, 2023). "As observed with MLR, the increased interaction score depended on the IgG4-Pro backbone: J014 on IgG1-KO backbone did not lead to increased interaction CD3+ T cells with CD34+ AML cancer samples." (PMID 35967294, 2022). "In these contexts, humanized mice have contributed with critical insights into the in vivo spatial and temporal effects of novel and exciting therapies (e.g., human CAR T cells targeting human tumors, including models with fully autologous cancer and CAR T cell, derived from CD34+ transplants)." (PMID 35865810, 2022). "Additionally, BK124.1 evoked massive apoptosis in multidrug resistant K562-MDR1 cells (IC50 = 2.16 μM), in CD34+ cells from CML patients (IC50 = 1.5 μM), and in the CD34+/CD38− subpopulation consisting of rare, drug-resistant cancer initiating stem cells." (PMID 35892900, 2022). "These include the cancer cell line LAD2 and CD34+ peripheral blood derived MCs (PBdMCs)." (PMID 35625799, 2022). "The differentiation of ex vivo expanded CD34 + cells through manipulation of RAS/MAPK, IGF-1R and TGF-β signaling pathways is an efficient approach for generating functional NK cells that can be used for cancer immunotherapy." (PMID 34098947, 2021).
cancer (continued). "Moreover, diminished eIF3f was detected in CD34+ cells exposed to MSC conditioned medium, which was in line with common suppression in diverse cancers." (PMID 34072546, 2021). "A selective activity of PEP005 in cancer cells was suggested, as it did not inhibit the growth of human neonatal fibroblasts and did not induce apoptosis in normal CD34(+) cord blood myeloblasts." (PMID 33922439, 2021). "We targeted the LTR2B family, which was the only one with AML-specific DHS enrichment and no enrichment in CD34+ cells, suggesting a more cancer-specific role than other A-DARs." (PMID 32665538, 2020). "For this purpose, CD34+ hematopoietic stem cells (HSC) are engrafted into immunocompromised mice by different approaches, followed by inoculation or transplantation of human cancer cell lines or PDX to generate diverse humanized mouse cancer models." (PMID 32331230, 2020). "In fact, CD34+ fibroblasts are generally absent in the stroma of most carcinomas as has been demonstrated for a variety of carcinoma entities." (PMID 32435886, 2020). "At both time points, cancer-associated stroma was positive for vimentin, α-smooth muscle actin (α-SMA) and D2-40, while it was negative for CD34." (PMID 30765891, 2019). "While the administration of 75 μg filgrastim 16–18 h prior to apheresis did not mobilize CD34+ cells, rather indicating an optimized condition for ex vivo induction of DCs from monocytes that led to an increase in the ratio of patients who could acquire immunity against cancer-associated antigens." (PMID 31546936, 2019). "CD34-positive staining identified vessels formed by endothelial cells (yellow arrow), whereas CD34-negative, PAS-positive vascular-like structures containing red blood cells formed by cancer cells or ECM were regarded as VM (red arrow)." (PMID 28599281, 2017). "Human CD34+ hematopoietic stem-cell engrafted NSG mice develop multi-lineage human immune cells and have become a popular, valid platform for infectious disease research and cancer biology, especially with respect to immune-oncology studies." (PMID 28196514, 2017). "Taken together, these may probably be due to GPX3 playing different roles in initial development of cancer, and GPX3 expressed heterogeneously among different cells types like in CD34+ cells and mesenchymal stem cells." (PMID 27891827, 2017). "SIRT1 is overexpressed in CD34+ AML, with a minimal role in normal hematopoietic cells but involvement in metabolism, cell cycle control, metabolism, DNA repair and survival of cancer cells." (PMID 28978059, 2017). "CD34, an epithelial marker and correlated with epithelial to mesenchymal transition, was negative both in hASCs alone and when co-cultured with cancer cells." (PMID 28102844, 2017). "Our data demonstrated that CD34+ and Lgr6+ cancer stem cells activate the ALT pathway in the absence of TRF2 expression and telomerase activity." (PMID 29113290, 2017). "As describe above, we identified differentially regulated genes between AML and normal cell lines (NB4/ CD34+) by identifying gene that have DNase-seq peaks within 150bp around the TSS in one condition (cancer or normal), but not in the other condition." (PMID 27145341, 2016). "VASH1-expressing endothelial cells were also co-expressed with CD34 but not with D2-40 in the same vessels in cancer tissues." (PMID 25797264, 2015). "Here we show that an immune system can be generated in immunodeficient mice using CD34+ HSPCs from bone marrow aspirates of non-metastasized carcinoma patients." (PMID 24830425, 2014). "We did not observe a correlation between the number of isolated CD34+ cells and patient age or carcinoma type." (PMID 24830425, 2014). "Strong EpCAM expression was restricted to the two carcinomas, while hemangiopericytoma cells were the only displaying CD34+hi expression; both groups of tumors systematically lacked CD45, B- and T-cell markers." (PMID 23472067, 2013).
cancer (continued). "Immunomagnetic selection based on one cell surface marker (i.e., CD34) can enrich for normal HSPC; however, this selection process is never 100%, and the positive fraction may contain contaminating cancer cells." (PMID 22312362, 2012). "It has been previously shown that sphere-forming cells isolated from primary carcinoma of the cervix uteri and samples from human endometrium are negative for CD34." (PMID 22284662, 2012). "Curcumin is a major component of turmeric that has shown cytotoxic activity in multiple cancers; however, its anti-cancer activity has not been well studied in DNR-insensitive CD34+ AML cells." (PMID 21595920, 2011). "Using DC vaccine as an anti-cancer therapy module has been facilitated by the development of methods to generate DCs from proliferating CD34+ precursors or from non-proliferating CD14+ monocytes." (PMID 22013914, 2011). "Besides, CD34 expression is also found on multiple cancer stem cells, but not lymphoid cells and is typically lost during cell maturation." (PMID 41296384, 2025). "The immune humanized cancer PDX model (firstly transplanted with human hematopoietic stem cells CD34+ for reconstitution of the human immune cells and followed by PDX transplantation) might be a better relevant model for studying the cancer-related immune response in immunotherapy." (PMID 40918454, 2025). "The IS analysis in transduced CD34+ HSPCs from P2 demonstrated a high polyclonality with low relative frequencies of the 10 most prominent ISs (<0.8%), 138 CISs with orders ranging from 2 to 6 and no ISs were found in proximity to cancer genes." (PMID 39062069, 2024). "For non-cancer studies, the miDRB-targeted exosome biogenesis genes for ferroptosis-inhibiting miRNAs are retrieved as follows: miR-19a-3p (SDC1, VPS4B, and MYO5B), miR-424-5p (VPS4A and MYO5B), miR-4291 (ATP9A, SMPD3, TSG101, and MYO5B), miR-522-3p (PDCD6IP), and miR-670-3p (CD34 and RAB27A)." (PMID 38892270, 2024). "Indeed, the widely used cancer data repositories like The Cancer Genome Atlas (TCGA) use data from the transcriptome of BMNCs as such, rather than CD34+ purified fractions, in their studies on AML." (PMID 37884893, 2023). "In human cancer, identification of MDSCs by CD34 expression was attempted, but this marker was not used much since the CD34+ subset may include hematopoietic progenitor cells." (PMID 36395389, 2022). "The authors revealed that PI − BI in carcinoma tissues was significantly higher than that in normal or benign tissues (P<0.001) and demonstrated that PI − BI corresponds with MVD, which was calculated by counting CD34-positive vascular endothelial cells (r=0.921, P<0.001)." (PMID 36338700, 2022). "The cancer stroma molecules CD34 and D2-40 were not different among the three groups." (PMID 34545095, 2021). "For example, ADT levels of EPCAM on cancer/epithelial cells (c0, c4, c8, c14 and c15), CD31 (PECAM1) and CD34 on endothelial cells (c7 and c9), CD146 (MCAM) on perivascular cells (c11), CD90 (THY1) and CD34 on CAFs (c13) and CD45 (PTPRC) on immune cells (c3, c5 and c12)." (PMID 33971952, 2021). "Many of these ERVs are also active in CD34+ progenitor cells and are therefore not cancer-specific, but they may nonetheless be used to support a gene expression programme that blocks cellular differentiation, a key hallmark of AML." (PMID 32665538, 2020). "The flow cytometry analysisof ASCs revealed that more than 90% of all cancer andnormal ASCs were positive for the stem cell specificmarkers, including CD90, CD105, CD44 and CD73, butthey were negative for the expression of hematopoieticspecific markers, such as CD45, CD34 and CD14." (PMID 31721539, 2020). "Immunohistochemistry (IHC) was nonspecific and inconsistent (positive for pancytokeratin, PAX8, and CDX2, and negative for CK7, CK20, ER, WT1, calretinin, CD31, CD34, and synaptophysin) and working diagnosis was a putative upper gastrointestinal versus mullerian cancer profile." (PMID 27171493, 2016).
cancer (continued). "Importantly, SIRT1 inhibition had less of an effect on proliferation and apoptosis of normal CD34+ cells, suggesting that SIRT1 might be a new target for eliminating CML cancer stem cells." (PMID 25749979, 2015). "Moreover, D2-40 has identified lymphatic invasion in many malignant tumors.Our results showed that there was no immunologic cross-reactivity between antibodies against D2-40 and CD34." (PMID 24040410, 2013). "CD34 was detected in endothelium and reactive stromal cells in some tumors but not cancer cells." (PMID 21124918, 2010). "Recent studies comparing these factors in the context of different types of cancer suggest that the use of CD105 as a marker of microvascular density (MVD) may provide better prognostic indicators of disease progression and prognosis than CD31 or CD34 in many types of cancer, including NSCLC." (PMID 39272978, 2024). "The present work is the first to demonstrate a CD34‐negative immunophenotype as a good prognostic factor in ALL, whereas high CD34 expression is associated with poor therapy response and an altered gene expression profile reminiscent of migrating cancer stem‐like cells." (PMID 35271751, 2022). "Similarly, NTRK3-KHDRBS1 was discovered in an infant with a CD34-positive spindle-cell skin tumor and is of particular interest due to the more recent identification of NTRK3 fusions as drivers in the development of rare cancer types, as well as the recent development of TRK inhibitors." (PMID 33281875, 2020). "However, both large and small carcinoma cells were totally c-Kit-negative, CD34-negative, αSMA-partially positive, PLAP-positive, SALL4-focally positive, AFP-negative, CD30-negative, glypican-3-slightly positive and Oct3/4-negative using immunohistochemical staining." (PMID 32990826, 2020). "Moreover, IBR2 effectively inhibits the proliferation of CD34+ progenitor cells from CML patients, suggesting that small molecule inhibitors of RAD51 may provide a novel class of broad-spectrum therapeutics for difficult-to-treat cancers." (PMID 25749979, 2015). "Also, the frequency of CD34+ HSPCs in carcinoma patients was similar to non-carcinoma patients." (PMID 24830425, 2014). "Clear cell carcinoid of lung: These clear cancer cells are diffuse positive for Syn, CgA, NSE, cytokeratin, and so on, as well as negative for HMB-45, Malen-A, CD34, and so on." (PMID 36800595, 2023). "The DNA ligase IV inhibitor, SCR-7, was also tested in K562 and primary CD34+ HSPCs edited with AAV6 and Cas9; unlike previous reports in human cancer cell lines and porcine fibroblasts, SCR-7 did not improve HDR editing in K562 cells or CD34+ HSPCs." (PMID 33535527, 2021). "By co-staining with anti-CD45, CD34 and TE7 antibodies, we were able to label the different subpopulations as leukocytes (CD45+), endothelial cells (CD34+), fibroblasts (TE7+) and lineage (LIN)-negative cells (i.e. carcinoma cells)." (PMID 32245446, 2020). "BMSCs collected from cancer primary sites or from bone marrow were epithelial marker (EPCAM), endothelial marker (CD31), hematopoietic marker (CD45 and CD34) and neutrophil marker (MPO) negative." (PMID 31819035, 2019). "Right panel shows the representative image of negative control staining for CD34 and PAS reaction in cancer tissues." (PMID 30833656, 2019). "All cell types were negative for haematopoietic cell markers CD45, CD34, CD19, CD14, human lymphocyte antigen-DR (HLA-DR), the carcinoma cell marker (c-MET) and EPCAM." (PMID 28419140, 2017). "As opposed to reported findings in AML, we showed that cancer stem cells from MDS samples derived from both CLEC12A positive and negative CD34+CD38− subpopulations." (PMID 27612176, 2016). "It is interesting that with the two most commonly used antibodies CD31 and CD34, the highest MVD was seen in Ni Types IV and Va, the patterns typical for low-grade and high-grade dysplasia or preinvasive cancer and not in Type Vb or Vc, which are attributed to invasive cancer." (PMID 31586562, 2021).